BRAF (B-Raf proto-oncogene, serine/threonine kinase)
Diseases named in the same sentence as BRAF in open-access papers (continued):
Sharing a sentence is not in itself a finding about the gene and the disease.
lymph node metastasis (continued). "Similar to NF1 and/or BRAF subtypes, patients with lymph node metastasis and/or ulceration had more RAS mutations than those without lymph node metastasis or ulceration." (PMID 32083130, 2020). "Five (62.5%) of eight patients with PTC with lymph node metastasis expressed a BRAF V600E mutation, while seven (77.78%) of nine PTC without lymph node metastasis harbored the mutation." (PMID 30694737, 2019). "Recent studies have begun to associate selected variant and fusions with BRAF V600E-like vs. RAS-like (or non-BRAF-non-RAS) pathway signaling, iodine metabolism, neoplasm histology, risk of lymph node metastasis, risk of recurrence, and risk of mortality." (PMID 31572297, 2019). "One case of PTC-FV harbored lymph node metastasis and was negative for the BRAF or NRAS mutation, while none of the PTMC-FV cases exhibited lymph node metastasis." (PMID 28680105, 2017). "The X-chromosome inactivation pattern and/or BRAF status had the same rate of discordance in patients with lymph node metastasis (3/9, 33.3%) and in patients without metastasis (1/3, 33.3%)." (PMID 25882744, 2015). "Although the results demonstrated that BRAF positive patients were more likely to have central lymph node metastases, the authors stop short of recommending PCND in BRAF positive patients but rather recommend the selective approach as outlined in the ATA guidelines." (PMID 22091417, 2011). "This suggests that lymph node metastasis may be related to RET and BRAF mutation, but not RAS mutation." (PMID 38734621, 2024). "These suggest that lymph node metastasis may be related to RET and BRAF mutation, but not RAS mutation." (PMID 38734621, 2024). "Infiltration depth, macroscopic classification, BRAF, carbohydrate antigen 19 − 9 (CA-199) levels, N stage, M stage, TNM stage, carcinoembryonic antigen levels, number of positive lymph nodes, vascular tumor thrombus, and lymph node metastasis were independent prognostic factors." (PMID 37386397, 2023). "Afirma XA results may offer important prognostic insights; for example, nodules with a non-RAS and non- BRAF molecular profile have lower rates of lymph node metastasis and extrathyroidal extension." (PMID 36909304, 2023). "In wild-type BRAF patients, the mean BRAF mRNA level was higher in cases with a tumor > 2 cm than those with a tumor ≤ 2.0 cm (189.4 vs. 163.8, p = 0.046), and was also higher in cases with lymph node metastasis than in those without lymph node metastasis (188.5 vs. 157.9, p = 0.040)." (PMID 27410688, 2016). "In terms of predicting PFS, among all tested variables associated with progression‐free survival (PFS) using Cox regression model, age, gender, lymph node metastasis (LNM), RAS status, and BRAF status did not affect PFS." (PMID 38746969, 2024). "In BRAF-mutant PTC, however, neither lymph node metastasis (HR: 1.34, 95%CI: 0.35–5.09) nor HT (HR: 0.69, 95%CI: 0.16–3.03) remained independent predictors of recurrence." (PMID 37190300, 2023). "Nevertheless, the paired lymph node metastasis stained negative for BRAFV600E and confirmed to be BRAF wild type." (PMID 25526463, 2014). "Furthermore, in the low-risk group of the training set, the survival status, pathological stage I-II, T1-2, no lymph node metastasis, no distant metastasis, distant occurrence location, no RFS event and wild-type BRAF occurred more times." (PMID 33777735, 2021).
pilocytic astrocytoma (188 papers, 2009 to 2026). Pilocytic astrocytoma is a rare subtype of low-grade glioma of the central nervous system characterized by a well circumscribed, often cystic, brain tumor with a discrete mural nodule and long, hair-like projections that extend from the neoplastic astrocytes. "BRAF mutations are present in various gliomas, including gangliogliomas, pilocytic astrocytomas, PXA, and epithelioid glioblastomas." (PMID 41357590, 2025). "One pontine DMG harbored a KIAA1549::BRAF fusion, a molecular alteration associated with pilocytic astrocytoma and diffuse leptomeningeal glioneuronal tumor and exceedingly rare in DMGs." (PMID 40237561, 2025). "This included patients with non-NF1 pilocytic astrocytoma with KIAA1549::BRAF or BRAF p.V600E mutation (stratum 1), NF1-associated pLGGs (stratum 3) and those with recurrent/progressive non-NF1 optic pathway and hypothalamic pLGGs (stratum 4)." (PMID 40422539, 2025). "The KIAA1549::BRAF fusion has been described in pilocytic astrocytoma, where it is associated with a favorable prognosis, and in pediatric low-grade astrocytoma." (PMID 39324010, 2024). "Four patients had medulloblastoma confirmed on histopathologic examination, with one patient affected by Li-Fraumeni syndrome; three patients had pilocytic astrocytoma, and one patient had BRAF-mutated ganglioglioma." (PMID 37695369, 2024). "For example, the identification of a BRAF fusion can lend credence to a diagnosis of histologically ambiguous pilocytic astrocytoma, or the presence of BRAF V600E mutation and deletion of CDKN2A/B gene by FISH or DNA testing can confirm the diagnosis of PXA." (PMID 38764578, 2024). "One notable exception was a pilocytic astrocytoma PDX (BT-40) that harbored the well-characterized BRAF-activating mutation V600E." (PMID 39510293, 2024). "Pilocytic astrocytoma (PA), the most common pediatric brain tumor, is driven by aberrant mitogen-activated protein kinase signaling most commonly caused by BRAF gene fusions or activating mutations." (PMID 37656187, 2023). "Other BRAF alterations, including BRAF gene fusions seen in the majority of pediatric pilocytic astrocytomas, encode constitutively active RAS-independent dimers." (PMID 37219686, 2023). "BRAF alterations included KIAA1549-BRAF fusion that is more specific of pilocytic astrocytomas (5 cases) and the BRAF V600E mutation that is more frequent in ganglioglioma (4 cases)." (PMID 37936887, 2023). "While BRAF fusions are associated with an indolent course in pediatric patients, in adults there was a bimodal survival distribution of pilocytic astrocytomas and other higher-grade pathologies with a more aggressive clinical course." (PMID 36854806, 2023). "In our hands, when only considering pilocytic astrocytoma cases, the BRAF V600E was associated with a worse outcome for both PFS and OS." (PMID 35363819, 2022). "For example, KIAA1549:BRAF fusion is mostly found in pilocytic astrocytoma and the BRAF V600E mutation is frequently detected in pilomyxoid astrocytoma and gangliogliomas." (PMID 35884462, 2022). "Among the LGG, 10 cases were positive for BRAF V600E mutation (4 gangliogliomas, 3 pilocytic astrocytoma, 2 pleomorphic xanthoastrocytoma and 1 diffuse astrocytoma)." (PMID 35363819, 2022). "Supratentorial pilocytic astrocytomas are more likely to harbor the BRAF V600E mutation, whereas posterior fossa and spinal cord pilocytic astrocytomas frequently harbor BRAF-KIAA1549 fusion oncogenes." (PMID 34685506, 2021). "When exploring the prevalence of BRAF alterations in different subtypes, KIAA1549:BRAF fusion and BRAF V600E mutations were seen in 50–85% and 9-15% of pilocytic astrocytomas, respectively and were mutually exclusive." (PMID 34360713, 2021).
pilocytic astrocytoma (continued). "The BRAF V600E mutation has been detected in pilocytic astrocytoma, ganglioglioma, diffuse astrocytoma and pleomorphic xanthoastrocytoma." (PMID 33557011, 2021). "A phase 2 trial demonstrated 20/25 patients with recurrent or refractory pilocytic astrocytoma harboring either BRAF V600E mutation or KIAA1549:BRAF fusion had either partial response or stable disease with selumetinib." (PMID 33415075, 2020). "As a second example, BRAF mutations or fusions are present in a diverse spectrum of neuroepithelial tumors, including ganglioglioma, pilocytic astrocytoma, and pleomorphic xanthoastrocytoma (PXA)." (PMID 32859279, 2020). "Another BRAF-related mutation observed in supratentorial hemispheric pilocytic astrocytomas, gangliogliomas, PXA, and dysembryplastic neuroepithelial tumor (DNET) is BRAF V600E." (PMID 32977537, 2020). "The majority of non NF1-associated pilocytic astrocytoma carries an activation of BRAF due to fusion of BRAF with KIAA1549." (PMID 31906320, 2020). "First, presumably the most common driver mutation in pilocytic astrocytoma (i.e. BRAF fusion) produces a similar set of gene expression changes regardless of tumor location/cell of origin." (PMID 33206716, 2020). "In the present study, we aim to determine the prevalence of BRAF V600E mutations in a series of ganglioglioma (GG) and pilocytic astrocytoma (PA) cases." (PMID 32879641, 2020). "Here we reported a novel recurrent p.V504_R506dup BRAF mutation specific to pediatric Pilocytic Astrocytoma." (PMID 30575814, 2019). "In contrast, only 9% of BRAF V600E mutations are seen in pediatric pilocytic astrocytomas and these mutations overlap with the most likely differential diagnosis of ganglioglioma." (PMID 31181803, 2019). "Especially the more common pilocytic astrocytoma (PA) and ganglioglioma (GG) are frequently associated with BRAF alterations." (PMID 31181803, 2019). "The few remaining mutations identified in pilocytic astrocytoma involve BRAF V600E mutations, KRAS hotspot mutations, NTRK fusions, or FGFR1 duplications." (PMID 31181803, 2019). "Low-grade astrocytomas, including pilocytic astrocytoma, were the most commonly tested tumor type, and as a result, the most common alteration was a BRAF fusion or variant (V600E or T599dup), present in 30.7% (n = 31/101) of cases." (PMID 31133068, 2019). "V600 E being the most common cancer-associated BRAF mutation and one often seen in gangliogliomas, pleomorphic xanthoastrocytomas, dysembryoplastic neuroepithelial tumors as well as a subset of pilocytic astrocytomas." (PMID 29701169, 2018). "The presence of BRAF fusions was considered a molecular hallmark of WHO grade I pilocytic astrocytoma with a typically favorable prognosis." (PMID 30279357, 2018). "Pilocytic astrocytomas typically contain a BRAF fusion but occasionally a BRAF V600E mutation, RAF1 fusion, intragenic duplication of FGFR1, or other rarer alterations are present." (PMID 29568396, 2018). "Accordingly, we identified BRAF V600E mutation in 43% of the gangliogliomas, in 33% of the diffuse astrocytomas in 13% of the pilocytic astrocytomas, but also in one anaplastic astrocytoma and one glioblastoma." (PMID 30558563, 2018). "A high percentage of pilocytic astrocytomas harbor a 7q34 duplication, resulting in the fusion of the gene encoding BRAF and KIAA 1549 gene." (PMID 30279357, 2018). "The protein encoded by KIAA1549 has been found to be fused to the BRAF oncogene in many cases of pilocytic astrocytoma." (PMID 26132924, 2015). "The BRAF V600E mutation occurs frequently in certain brain tumors such as pleomorphic xanthoastrocytoma, ganglioglioma, and pilocytic astrocytoma, and less frequently in epithelioid and giant cell glioblastoma." (PMID 25885250, 2015). "The KIAA1549:BRAF fusion gene was initially thought to be highly specific for pilocytic astrocytomas thereby suggesting a useful diagnostic biomarker for a tumor with varied and challenging histology." (PMID 24716189, 2014).
pilocytic astrocytoma (continued). "One recent study of 51 pilocytic astrocytomas suggests that the presence of a KIAA1549:BRAF fusion should be associated with a pilocytic classification, while a BRAF V600E mutation is more prevalent in non-pilocytic gliomas." (PMID 23717811, 2013). "Another activating BRAF mutation that is almost exclusively found in pilocytic astrocytomas is the KIAA1549-BRAF fusion, found in 66–100% of these tumors." (PMID 24298448, 2013). "Anatomically, BRAF V600E mutations have been associated with extracerebellar pilocytic astrocytomas (instead of infratentorial ones)." (PMID 23717811, 2013). "In contrast, pilocytic astrocytomas -as recently indicated- are molecularly characterized by gene duplication/fusion or mutation of the BRAF gene on 7q34." (PMID 19333441, 2009). "An argument can be made to interrogate even lower grade gliomas such as Pilocytic Astrocytomas and provide early detection of BRAF mutations that could inform clinical and radiological monitoring." (PMID 41357590, 2025). "However, these syndromic tumors have a different genetic driver within the MAP kinase pathway compared to most sporadic pilocytic astrocytomas and gangliogliomas which typically harbor BRAF fusion or mutation." (PMID 35945463, 2022). "BRAF fusions are associated with a favorable prognosis, in part related to B-raf’s role in promoting oncogene-induced senescence in tumors, as well as its frequent occurrence in pilocytic astrocytomas, which inherently have favorable outcomes." (PMID 36147920, 2022). "However, when only considering pilocytic astrocytoma, the BRAF V600E mutation was associated with a decreased OS (Log-rank (Mantel-Cox) Test, P<0.0001) and PFS (Log-rank (Mantel-Cox) Test, P = 0.0135)." (PMID 35363819, 2022). "The BRAFV600E mutation is rare in adult-type diffuse gliomas and can occasionally be used to distinguish pilocytic astrocytoma or pleomorphic xanthoastrocytoma from a diffuse astrocytoma, even though BRAF fusions are more frequent than this mutation in these subtypes." (PMID 35693015, 2022). "Besides BRAF point mutations, particularly in pilocytic astrocytomas, KIAA1549–BRAF gene fusions have been found." (PMID 35875139, 2022). "Genetic mutations in the proto-oncogene B-Raf gene, BRAF, cause pilocytic astrocytoma." (PMID 33671362, 2021). "This underlying pathogenesis of RGNT is different than other low-grade glioneuronal tumors such as ganglioglioma and pilocytic astrocytoma that typically involve a solitary pathogenic alteration (e.g. BRAF mutation or fusion) causing activation of the MAP kinase signaling in isolation." (PMID 32859279, 2020). "The BRAF V600E mutation was observed in CNS tumors, e.g., in 66% of pleomorphic xanthoastrocytoma, 51% of dysembryoplastic neuroepithelial tumor, 18-57% of ganglioglioma, 5-15% of pilocytic astrocytoma, and 1% of glioblastoma." (PMID 32879641, 2020). "Therefore, the primary aim of this study was to determine BRAF V600E mutation status in patients with rare CNS tumors—ganglioglioma and pilocytic astrocytoma." (PMID 32879641, 2020). "In the early phase 2 result, selumetinib was effective in treating children with recurrent/refractory low-grade glioma (LGG), including those with neurofibromatosis type 1 (NF-1)-associated LGG and pilocytic astrocytomas (PA) harboring BRAF V600E mutation or BRAF-KIAA 1549 fusion." (PMID 28954413, 2017). "In murine xenografts of a pilocytic astrocytoma with mutated BRAF V600E, treatment with PLX4720 + everolimus led to a statistically significant survival advantage, when compared to treatment with vehicle alone (p = 0.0002), PLX4720 alone (p = 0.0126), or everolimus alone (p = 0.0031)." (PMID 23717811, 2013). "Alterations involving the mitogen-activated protein kinase (MAPK) pathway are central drivers of pediatric and adult low-grade gliomas (LGGs), with BRAF fusions representing a dominant oncogenic mechanism in pilocytic astrocytoma." (PMID 41659712, 2026).
pilocytic astrocytoma (continued). "Focal copy-number variations on Chr7q suggestive of BRAF fusions were observed in 5/6 fusion-positive pilocytic astrocytomas." (PMID 41834733, 2026). "A pivotal discovery occurred in 2008, when a tandem duplication in the BRAF gene was identified in 65%–75% of low-grade pilocytic astrocytomas." (PMID 41050069, 2025). "BRAF fusions occur in 30–40% of these tumors and in 70–80% of pilocytic astrocytomas, with up to 75% of pLGG patients exhibiting BRAF alterations." (PMID 40430547, 2025). "The BRAF V600E mutation has been reported in GG, polymorphous low-grade neuroepithelial tumor of the young (PLNTY), pleomorphic xanthoastrocytoma, pilocytic astrocytoma, DNT, and MAPK pathway-altered diffuse low-grade glioma (dLGG)." (PMID 39081340, 2024). "BRAF-fusions have been detected in different primary brain tumors, particularly in pilocytic astrocytoma (WHO CNS grade 1)." (PMID 38779936, 2024). "The KIAA1549:BRAF fusion gene is considered a driver in pilocytic astrocytoma, and constitutively activates the MAP kinase pathway." (PMID 38791993, 2024). "One spinal tumor (case #2) in this group contained areas reminiscent of pilocytic astrocytoma and harbored KIAA1549::BRAF fusion together with ATRX loss being highly suggestive of HGAP7." (PMID 37891325, 2023). "BRAF rearrangements are common in pediatric LGG, particularly pilocytic astrocytoma, and linked with favorable survival." (PMID 36854806, 2023). "Nearly 100% of pilocytic astrocytoma have mutations involving the MAPK/ERK signalling pathway regulation, where BRAF kinase alterations are considered to be the characteristic hallmark." (PMID 37033188, 2023). "The rate of BRAF genetic alteration in the grade II samples (3/9, 33%) was significantly higher than the reported rate for grade I pilocytic astrocytoma." (PMID 35574540, 2022). "treated an adult patient with a BRAF V600E pilocytic astrocytoma with vemurafenib, a B-raf inhibitor, and cobimetinib, a MEK inhibitor, with 1-year follow-up showing tumor stability and reduction of T2 cord signal cranial and caudal to the lesion." (PMID 36147920, 2022). "In two of these tumours, duplication of the 3′ red signal was observed, suggesting the presence of the common KIAA1549:BRAF tandem‐duplication characteristic of pilocytic astrocytoma." (PMID 35836307, 2022). "We used the ddPCR approach reported by Appay and co-workers to investigate DNA extracted from FFPE samples of pilocytic astrocytomas of 20 patients for BRAF duplication as a surrogate marker for KIAA1549-BRAF fusions." (PMID 35361262, 2022). "Of note, given that BRAF V600E is much less common in histologically defined pilocytic astrocytomas than BRAF tandem duplication, it was of critical importance to assess for this variant despite a lower pretest probability given the histology." (PMID 35475276, 2022). "There are also increased chances of mutations of BRAF, constant chromosome gains at 7q34, and mutations of KRAS activating the MAPK pathway in sporadic pilocytic astrocytoma." (PMID 35888021, 2022). "For example, KIAA1549- BRAF fusion is mostly found in pilocytic astrocytoma (PA), while BRAF V600E is frequently detected in pleomorphic xanthoastrocytoma (PMA) and gangliogliomas." (PMID 33869004, 2021). "The KIAA1549/BRAF fusion was detected in 1 out of 8 pilocytic astrocytomas in our cohort and in two grade II astrocytomas (all 3 in methylation cluster PA-like)." (PMID 32555164, 2020). "Early studies examining copy number alterations in pilocytic astrocytoma identified focal gains at 7q34 which included the BRAF gene." (PMID 32164789, 2020). "Sporadic pilocytic astrocytoma frequently harbors somatic alterations in BRAF, with rare pilocytic astrocytomas containing alterations in FGFR1 and NTRK2." (PMID 32082673, 2020). "Fourth, this analysis is restricted to a single subtype of pilocytic astrocytoma; namely, those occurring in the cerebellum with a BRAF fusion." (PMID 33206716, 2020).